ENSG00000267314 (novel protein, readthrough VMAC-CAPS)
Gene: Protein-coding gene on chromosome 19 (5,904,841 to 5,914,707, forward strand). Ensembl gene ENSG00000267314.
Genetic constraint (gnomAD): Missense variants: 119 observed, 66.19 expected, observed/expected ratio (o/e) 1.8, 90% interval 1.54 to 1.97. Synonymous variants: 46 observed, 25.52 expected, observed/expected ratio (o/e) 1.8, 90% interval 1.39 to 1.97.